MYCN (MYCN proto-oncogene, bHLH transcription factor)
Diseases named in the same sentence as MYCN in open-access papers (continued):
Sharing a sentence is not in itself a finding about the gene and the disease.
neuroblastoma (continued). "Neuroblastomas with both MYCN and FAK have been found to be over-expressed in patients with higher risk disease and poorer prognosis." (PMID 31519958, 2019). "MYCN-mediated upregulation of Malat1 provides one mechanism in which its amplification can lead to increased metastasis in neuroblastoma patients." (PMID 31616462, 2019). "Synergistic cytotoxicity was observed for the drug combination in all of the 5 neuroblastoma cell lines tested, including MYCN amplified lines and in cancer stem cells." (PMID 31664947, 2019). "In this regard, THZ1 has been shown to inhibit leukemia, lung cancer, MYCN gene-amplified neuroblastoma, and esophageal squamous cell carcinoma progression in mice." (PMID 31346162, 2019). "CX-5461 significantly inhibited the growth of established MYCN-amplified neuroblastoma grown as xenografts in nude mice." (PMID 30542116, 2019). "In in vitro experiments, MYCN amplification in neuroblastoma cells is related to cell motility and invasion ability." (PMID 30836897, 2019). "To functionally investigate the role of MycN on the sensitivity of neuroblastoma cell lines to the ribosome biogenesis inhibitors, we utilized the SHEP-TET21N model system." (PMID 30542116, 2019). "Accordingly, MYCN silencing has been reported to induce cell cycle arrest, apoptosis and cytodifferentiation of neuroblastoma cells, and pharmacological inhibition of MYCN activities is being actively pursued." (PMID 31293052, 2019). "Amplification of the MYCN oncogene and consequent over-expression of the N-Myc oncoprotein occur in approximately 25% of human neuroblastoma tissues and correlate with poor patient prognosis." (PMID 31690716, 2019). "MYCN amplification directly correlates with the clinical course of neuroblastoma and poor patient survival, and serves as the most critical negative prognostic marker." (PMID 30691436, 2019). "Approximately 25% of neuroblastoma tumors harbor amplification of MYCN that strongly correlates with a poor prognosis." (PMID 31396265, 2019). "Overall, survivin would be a useful biomarker and prognostic marker in neuroblastoma depending on MYCN amplification and stage." (PMID 30609639, 2019). "The prototypic route for disrupted differentiation of NCCs leading to neuroblastoma depends on MYCN amplification, which in turn leads to overexpressed MYCN protein directly repressing genes required for sympathetic nervous system terminal differentiation." (PMID 31040767, 2019). "11q23 is the most commonly deleted 11q region, and interphase fluorescence in situ hybridization (FISH) has been previously confirmed as a reliable method for detecting MYCN status in bone marrow metastases of neuroblastoma." (PMID 31685009, 2019). "Previous studies have revealed that amplification of MYCN increases neuroblastoma cell growth through glutathione biosynthesis and glutamine uptake, thus suggesting MYCN reprograms neuroblastoma metabolism." (PMID 31624245, 2019). "Taken together, the data suggest that lncNB1 expression is the highest in neuroblastoma compared with all other human cancers, and correlates with MYCN gene amplification and expression." (PMID 31690716, 2019). "The delayed neuroblastoma onset in Th-MYCN/Casp2−/− mice, previously highlighted the tissue/context specific role for caspase-2 in tumor suppression." (PMID 30670683, 2019). "Next, the association between survivin expression and overall survival of neuroblastoma patients was analyzed according to MYCN amplification and stage." (PMID 30609639, 2019). "MYCNOS18 and IGF2BP116 promote MYCN-driven neuroblastoma metastasis and tumorigenesis, respectively, RNF21727, GRIK328, and SLCO5A129 promotes leukemia, breast and colon cancer." (PMID 31690716, 2019). "Tumor ploidy was identified as a prognostic factor around the time the role of MYCN amplification in neuroblastoma was identified." (PMID 30754710, 2019). "In this context, MYCN further promotes gene expression program induced by the ADRN CRC in neuroblastoma cells." (PMID 31819055, 2019).
neuroblastoma (continued). "It has been previously demonstrated that MYCN is able to compensate MYC activity in neuroblastoma cell lines and primary tumors, a mutual regulatory loop existing between them." (PMID 31748534, 2019). "Accordingly, CdK2 inhibition has been shown to slow down the growth of MYCN-amplified neuroblastoma cells and of other MYC-driven tumors." (PMID 31341534, 2019). "Here, we identify the transcriptional signature driven by LMO1 in combination with MYCN in neuroblastoma cells." (PMID 31819055, 2019). "Campbell reviewed 4,672 patients with neuroblastoma and found that patients with MYCN amplification had lower event-free survival and lower overall survival." (PMID 31338261, 2019). "Fortunately, MYCN amplification is found to co-occur with AURKA (encoding Auror-A kinase) gene amplification in NEPC, in a similar way to that in neuroblastoma." (PMID 30657058, 2019). "Genetic screens have been used to identify genes that are synthetic lethal to MYCN amplification/overexpression, leading to preclinical evaluation of many new agents in neuroblastoma." (PMID 35582571, 2019). "Enforced ELOVL2 expression in MYCN-amplified neuroblastoma cells led to decreased cell growth and counteracted the growth-promoting effect of MYCN overexpression both in vitro and vivo." (PMID 31856871, 2019). "IBL‐202/301 treatment of PDX cells and neuroblastoma cell lines resulted in unchanged MYCN mRNA levels (Fig EV2D) but pronounced decreases in N‐Myc protein levels." (PMID 31310053, 2019). "Amplification of the MYCN oncogene is present in ~25% of all neuroblastomas and is a marker for aggressive tumors, and in line with a differentiated phenotype, we detected lower N‐Myc expression in our PDX cells following IBL‐302 treatment." (PMID 31310053, 2019). "The International Neuroblastoma Risk Group (INRG) defined 16 different patient risk categories based on the INRG stage, tumor histology, and grade of tumor differentiation, MYCN status, 11q status, ploidy, and anaplastic lymphoma kinase amplification." (PMID 31692914, 2019). "Even when whole-genome sequencing of neuroblastoma was conducted, few recurrent gene alterations (MYCN, ALK, ATRX and TERT) were identified." (PMID 29311760, 2018). "BLF1 induced cell death in MYCN-amplified neuroblastoma with high potency similar to saporin, but had only a cytostatic effect on non-MYCN amplified cells at the concentrations tested." (PMID 29954071, 2018). "After treatment with NBT, the expression levels of MRP1 and MYCN decreased in A549/ADR cells in a time-dependent manner, consistent with the previous report that MRP1 is a downstream transcriptional target of MYCN in neuroblastomas." (PMID 30486290, 2018). "Inactivation of eIF4A appears to concomitantly target several key pathways involved in proliferation and cell survival of MYCN amplified neuroblastoma, making eIF4A a highly attractive target for the treatment of MYCN-amplified tumours." (PMID 29954071, 2018). "Of further interest, re-analysis of published data showed that MYCN transcriptionally activates FOXM1 in neuroblastoma cells." (PMID 30504901, 2018). "In the neuroblastoma cells, the increased MYCN levels induced expression of the miR-17-92 cluster at transcriptional level by direct binding to its promoter." (PMID 29547527, 2018). "Treatment of children > 18 months of age with widely disseminated neuroblastoma (stage 4) and those < 18 months with MYCN-amplified stage 4 disease remains one of the greatest challenges for pediatric oncologists." (PMID 30027525, 2018). "Depletion of expression of these genes resulted in suppression of colony formation and induction of apoptosis in MYCN amplified neuroblastoma cell lines." (PMID 30326621, 2018).
neuroblastoma (continued). "Its two paralogs, N-Myc and L-Myc, which are encoded by MYCN and MYCL genes, were respectively identified in neuroblastoma and lung cancer as more tissue-specific factors." (PMID 30597997, 2018). "TrkB and BDNF co-expression is detected in more aggressive neuroblastomas especially with MYCN amplification." (PMID 30034627, 2018). "That being said, the BCL2 inhibitors navitoclax and venetoclax were studied in both in vitro and in vivo models of neuroblastoma with encouraging results in MYCN-amplified cell lines and tumors." (PMID 30326621, 2018). "Here we combined whole-genome shRNA library screening and computational master regulator inference analysis to identify novel drug targets for MYCN-amplified neuroblastoma." (PMID 29880876, 2018). "Our study, for the first time, showed that Halofuginone effectively down-regulated MYC and MYCN proteins in MYC family driven neuroblastoma cells." (PMID 29464082, 2018). "How MYCN expression alters the biology and clinical responsiveness of pediatric neuroblastoma remains poorly defined." (PMID 29755654, 2018). "Downregulation of MYCN via siRNA has previously been shown to induce caspase 3 activation and apoptosis in MYCN amplified neuroblastoma." (PMID 29954071, 2018). "Expression of this protein correlated with a lower stage of the disease and a low level of MYCN amplification, whereas most of the c-kit-positive neuroblastomas represented differentiated (44.7%) or slightly differentiated (18.8%) tumors." (PMID 30116755, 2018). "In neuroblastoma, NTRK1 expression is associated with benign clinical features (e.g., young age, favorable pathology and non-MYCN amplified genetic status), tumor cell differentiation and good outcome." (PMID 29947893, 2018). "Very recently, human NCSC derived from hESC have been transformed by MYCN to form neuroblastoma in vivo." (PMID 30515222, 2018). "We demonstrate that TFAP4 is a direct target of MYCN in neuroblastoma cells, and that its expression and activity strongly negatively correlate with neuroblastoma patient survival." (PMID 29880876, 2018). "It is to be noted that SK-N-SH colonies, representing non-MYCN amplified neuroblastoma, were slower to grow and smaller in size than NGP cell colonies." (PMID 29515779, 2018). "It was also shown that MYCN amplification, a well-known bad prognosis factor for neuroblastoma, leads to downmodulation of MHC class I proteins." (PMID 30116755, 2018). "Caspase 3 activation and induction of apoptosis in a MYCN dependent manner was also observed following BLF1 treatment, demonstrating selective cytotoxicity of this toxin towards MYCN-amplified neuroblastoma cell lines." (PMID 29954071, 2018). "Further studies also reported that MYCN and common ALK mutations exert a role in neuroblastoma tumour initiation using neural crest progenitor cell lines MONC-1 and JoMa1." (PMID 30515222, 2018). "Overall, these results demonstrate that TFAP4 regulates proliferation in MYCN-amplified neuroblastoma." (PMID 29880876, 2018). "MYCMI-6 has GI50s as low as 0.5 μM in neuroblastoma and Burkitt’s lymphoma cells with deregulated MYCN/MYC, which is much more potent in comparison to most of the previously reported MYC:MAX inhibitors, such as 10058-F4, 10058-F4 analogues and 10074-G5." (PMID 29968736, 2018). "A recent study reported that transgenic expression of LMO1 alone failed to induce tumorigenesis in a zebra fish model, but acted as a synergist of MYCN, an oncogene amplified in ~20% of neuroblastoma." (PMID 30406033, 2018). "In both cases, MYC family-driven neuroblastomas with MYCN protein (+) or either protein (+) were more likely to have prominent nucleoli." (PMID 29464082, 2018).
neuroblastoma (continued). "In contrast, more than 60% of non-MYCN amplified High-MKI neuroblastomas were MYCN protein (−)/(+/−) and MYC protein (−)/(+/−)." (PMID 29464082, 2018). "According to the Children's Oncology Group (COG) assignment, age at diagnosis, the stage of disease, MYCN amplification, the International Neuroblastoma Pathology Classification and DNA ploidy are employed to stratify risk groups." (PMID 30405689, 2018). "We previously reported on the radio-sensitivity effect and inhibition of tumorsphere self-renewal of targeting a stem marker, L1-CAM, for knock-down in the human MycN-amplified IMR-32 neuroblastoma cells." (PMID 29298329, 2018). "This region is in part overlapping the region that is known to be gained in MYCN amplified neuroblastoma." (PMID 29492199, 2018). "Aurora A forms a complex with MYCN in MYCN-amplified neuroblastoma cells, protecting MYCN from proteasomal degradation during mitosis." (PMID 30027525, 2018). "Due to the cytotoxic and cytostatic effects of somatostatin, the expression of SSTRs has been found to inversely correlate with MYCN amplification and to positively correlate with survival of patients with differentiated neuroblastomas." (PMID 30018737, 2018). "Assessing the regulation of TFAP4 by MYCN/MYC, we found that high TFAP4 expression correlates with high MYCN or MYC expression in neuroblastoma cell lines and in the TARGET cohort of patients." (PMID 29880876, 2018). "Because MYCN overexpression has been identified as a strong predictor of poor outcomes in neuroblastoma we investigated the effects of HCI-2509 on NGP cells- a MYCN amplified neuroblastoma cell line." (PMID 29515779, 2018). "MYCN was first identified in neuroblastoma as a c-myc-related oncogene, and is amplified in ~25% of neuroblastoma cases." (PMID 29880876, 2018). "MYCN is a stem cell transcription factor and drives cell proliferation, survival and dedifferentiation in neuroblastoma cells." (PMID 29515779, 2018). "More effective and less toxic therapeutic approaches are urgently needed to overcome the poor prognosis of MYCN-driven tumors, such as high-risk/MNA neuroblastomas." (PMID 30166519, 2018). "We further validated synthetic lethality of TFAP4 with MYCN amplification in vitro and in vivo in a range of neuroblastoma cell lines." (PMID 29880876, 2018). "Further, the rate-limiting enzyme of polyamine synthesis ODC-1 is a direct downstream target of MYCN (and c-MYC), directly linking deregulation of polyamine metabolism to high-risk neuroblastoma, often characterized by MYCN amplification (reviewed in66)." (PMID 29968769, 2018). "Here, we describe DNA copy number and whole exome mutation analysis in a total of 36 matched tumor/normal samples from genetically engineered neuroblastoma mouse model systems driven by MYCN, ALKF1174L, MYCN/ALKF1174L or Lin28b." (PMID 29492199, 2018). "Further, the MYCMI-6, MYCMI-11 and MYCMI-14 efficiently inhibited anchorage-independent growth of MYCN-amplified neuroblastoma cells with GI50 values of <0.4, 5 and 0.75 μM, respectively." (PMID 29968736, 2018). "A number of neuroblastoma cell lines (typically MYCN-amplified (MNA)) have been shown in culture to slow or cease cell division and begin to extend axons in response to retinoic acid (RA)." (PMID 29301505, 2018). "As expected, the vast majority (103/120, 85.8%) of MYCN amplified High-MKI neuroblastomas overly expressed MYCN protein, including 2 tumors also having simultaneous MYCN and MYC protein expression." (PMID 29464082, 2018). "This is prototypically exemplified by neuroblastoma, where MYCN amplification occurs in about 25% of the cases." (PMID 30166519, 2018). "Here we show that LSD1 inhibition with HCI-2509 has a potential role to play in downregulation of the MYCN upregulated genes of MYCN amplified neuroblastoma which translates to growth inhibitory effects." (PMID 29515779, 2018).
neuroblastoma (continued). "In concordance with this, we demonstrated that siRNA-mediated knockdown of MYCN increases the proportion of MYCN-amplified neuroblastoma cells in the G1 phase of the cell cycle." (PMID 29719597, 2018). "In this study we look in greater detail at the anti-proliferative effect of BLF1 in neuroblastoma cells with an emphasis on MYCN amplification status." (PMID 29954071, 2018). "In contrast to GU, the MYC gene family expression was limited to MYCN, a feature shared with neuroblastomas." (PMID 29487377, 2018). "Here, we explored the involvement of MRE11 in neuroblastoma as a model for MYCN-driven tumors and addressed the possibility to target the MRN complex to trigger intolerable levels of RS-dependent DNA damage in MNA/high-risk tumors." (PMID 30166519, 2018). "Subsequently, these cells were transduced with MYCN and injected into mice to generate neuroblastomas." (PMID 30504901, 2018). "In human MYCN-amplified neuroblastoma cell lines, inhibition of ODC led to increased expression of cyclin-dependent kinase inhibitor p27Kip1, retinoblastoma protein (Rb) hypophosphorylation, and cell cycle arrest." (PMID 29419804, 2018). "Further investigation of BLF1 as an immunotoxin and targeting of this enzyme to MYCN-amplified neuroblastoma or other Myc-driven cancers will therefore be of high interest." (PMID 29954071, 2018). "Both genetic and chemical inhibition of EZH2 in MYCN-amplified neuroblastoma mouse models resulted in decreased tumor burden." (PMID 30326621, 2018). "Although several alterations including MYCN amplification, TERT rearrangements, ALK and ATRX mutations are identified to be associated with neuroblastoma, detection of potential mutated drivers is still hampered by the low mutation frequency." (PMID 30012197, 2018). "MYCN gene amplification is a common event in untreated neuroblastomas, reported in as many as 38% of untreated patients, with a high degree of correlation with advanced disease stages and poor prognosis." (PMID 29515779, 2018). "Specific inhibition of hyperactive rRNA synthesis and protein translation was shown to be an effective way to suppress MYC/MYCN protein expression and neuroblastoma growth." (PMID 29464082, 2018). "Here, we demonstrate that TFAP4 is a direct target of MYCN, and that its expression is significantly upregulated in stage 4 MYCN-amplified neuroblastoma." (PMID 29880876, 2018). "We demonstrate that TFAP4 functions to promote proliferation and inhibit differentiation in MYCN-amplified neuroblastoma." (PMID 29880876, 2018). "TERT mutations were found on whole genome sequencing in high risk neuroblastoma, although these only occurred in the absences of ATRX mutations or MYCN amplification." (PMID 30154341, 2018). "Primary cultures of mouse neural crest cells overexpressing MYCN also formed neuroblastoma and osteosarcoma in the mouse model." (PMID 30116755, 2018). "Three small molecule inhibitors of BET have been investigated in pre-clinical models and have been shown to downregulate MYCN expression, induce cell cycle arrest and apoptosis in neuroblastoma cells and inhibit tumor growth in mouse models." (PMID 30326621, 2018). "Izumi et al19 reported that TRIM32 has the capacity to up‐regulate asymmetric cell division, which works against MYCN and can be considered a tumour suppressor in human neuroblastoma cells." (PMID 30079558, 2018). "This analysis identified transcriptional factor activating protein 4 (TFAP4) as the top synthetic lethal candidate and MYCN-amplified neuroblastoma subtype MR." (PMID 29880876, 2018). "DFMO alone significantly delayed tumor initiation in neuroblastoma-prone TH-MYCN mice (homozygous for the MYCN transgene), although all mice eventually succumbed to the tumor." (PMID 29799508, 2018).